LDHA (lactate dehydrogenase A)
Diseases named in the same sentence as LDHA in open-access papers (continued):
Sharing a sentence is not in itself a finding about the gene and the disease.
cancer (continued). "LDHA catalyzes the conversion of pyruvate to lactate with concomitant oxidation of NADH to NAD+, which plays an essential role in metabolic pathways of the cancer cells." (PMID 33858449, 2021). "In 2016, a research team cataloged GNE-140 from a high throughput screening of two million compounds as having ability to inhibit LDHA, LDHB, and LDHC with IC50s in the nanomolar range, which could entirely block lactic acid production in cancer cells." (PMID 34944395, 2021). "However, in hypoxic cancer cells, active pyruvate dehydrogenase kinase (PDK) inhibits PDH, resulting in the uncoupling of the tricarboxylic acid (TCA) cycle and stimulation of lactate dehydrogenase A (LDHA)." (PMID 33806179, 2021). "The mechanism of LDHA-induced chemoresistance can be summarized as follows: First, as a direct target of the HIF-1A and C-MYC oncogenes, LDHA promotes biosynthesis and glycolysis, ensuring energy supply and proliferation of cancer cells." (PMID 34540667, 2021). "Importantly, patients with PTC cancers who had increased glucose uptake assessed by 18FDG PET scans displayed lower levels LINC00671 and higher levels of STAT3 and LDHA expression." (PMID 34404767, 2021). "For this reason, it is not surprising that many cancers demonstrate a selective over-expression of LDH-A and that the LDHA gene is a direct target of the c-Myc (Myc) oncoprotein, which also drives glycolysis." (PMID 33808495, 2021). "By using an inducible cell line in which the DIO2 gene can be overexpressed upon doxycycline (DOX, 2 μg/mL, Clontech, Mountain View, CA, USA) administration, we show that TH fosters the expression of key mediators of the Warburg effect of cancer cells, namely, GLUT1, PKM2 and LDHA." (PMID 34205977, 2021). "However, cancer cells which depend on FAS and glutamine decomposition are unaffected by LDHA inhibitors, since these cells rely on a mitochondrial function to produce ATP once the production of lactate is blocked." (PMID 35006438, 2021). "Several clinical and pre-clinical studies have further analyzed the effects of both selective and non-selective inhibitors of LDHA on cancer cells." (PMID 34367959, 2021). "Furthermore, QUE effectively suppressed cancer growth and proliferation in MCF-7 and MDA-MB-231 cells and decreased the level of glycolysis-related enzymes including LDHA." (PMID 32843908, 2020). "Based on the observations of LDHA- and LDHB-mediated cancer progression, we can speculate that LDHC could be involved in metabolic reprograming of cancer cells." (PMID 31932876, 2020). "Elevated levels of LDHA, PDK-1, and MCT-4 are considered hallmarks of cancers with Warburg Effect." (PMID 31936895, 2020). "However, it is still largely unclear how a cancer cell orchestrates the activities of PKM2 and LDHA to promote aerobic glycolysis and dampen the TCA cycle." (PMID 32572027, 2020). "Treatment with LDHA inhibitors such as oxamic acid, FX11, galloflavin, and 1-(phenylseleno)-4-(trifluoromethyl) benzene (PSTMB) demonstrate anti-proliferative effects in TNBC and other cancer models." (PMID 33324565, 2020). "Unlike other subunits, LDHA is primarily expressed in cancer cells and contributes to tumorigenesis." (PMID 31523182, 2019). "Specifically, LDHA is often upregulated in neoplastic tissues and, through actively transforming pyruvate to lactate, ensures ATP production and NAD regeneration, both essential in supporting cancer cell proliferation." (PMID 31480557, 2019). "Interestingly, cMyc and HDAC3 constitutes a positive feedback loop, which is connected by pyruvate: cMyc decreases pyruvate levels by promoting PKM2 and LDHA levels, consequently decreasing inhibition to HDAC3 and protecting cancer cells from apoptosis." (PMID 30866966, 2019). "Taken together, these data demonstrate that LDHB, but not LDHA, controls the basal autophagic flux of oxidative cancer cells, and silencing LDHB inhibits basal autophagy, cancer cell proliferation, and also leads to apoptosis." (PMID 31035592, 2019).
cancer (continued). "Based on the potential therapeutic value in targeting metabolism for the treatment of cancer, an organic arsenical PDT-BIPA was fabricated, which exerted selective anti-cancer activity in vitro and in vivo via targeting lactate dehydrogenase A (LDHA) to remodel the metabolic pathway." (PMID 31835667, 2019). "Some data, as knocking down LDHB, showed no apparent effect (similarly to LDHA) on apoptosis induction in cancer cells and silencing of the LDHB gene does not increase the cellular NADH/NAD+ ratio in these cells." (PMID 31035592, 2019). "Cancer cells dependent on glutamine decomposition and fatty acid synthesis are not affected by LDHA inhibitors, because these cells are more dependent on mitochondrial function to produce ATP once the production of lactic acid is inhibited." (PMID 30403008, 2018). "One focuses on the regulation of glycolytic flux-related proteins including Gluts, MCTs, lactate dehydrogenase A (LDHA), HK2, and PKM2.5, 6 This strategy aims to directly regulate the glucose supply and glycolytic pathways to control the energy production in cancer cells." (PMID 28230866, 2017). "LDHA is known as the M subunit and, although predominantly found in the heart, it plays many roles both in non-neoplastic and cancer cells." (PMID 28970582, 2017). "LDHA (Lactate Dehydrogenase A) is an enzyme that catalyzes the conversion of pyruvate to lactate and produces NAD+, a key metabolic step in anaerobic glycolysis under hypoxia and aerobic glycolysis in cancer cells in what is known as the Warburg effect." (PMID 28642487, 2017). "This, combined with a notable reduction in other known cancer-related proteins such as PDK and LDHA, suggests Lin28’s role as an oncogene itself may be overstated and may be amenable as an in vitro therapeutic target in certain circumstances." (PMID 27230676, 2016). "To complement these data, we investigated the effects of docetaxel on the expression of HIF-1α target genes (Glut1, CA9, LDHA, and BNIP3) involved in the metabolism of cancer cells and pro-apoptotic genes (CASP3, CASP8, and CASP10) in siJNK2-transfected MDA-MB-231 cells under hypoxic conditions." (PMID 27263528, 2016). "Our results indicate that mutant IDH1 cells, on the other hand, reduce glucose uptake and concomitant lactate production, in addition to silencing LDHA expression, making their metabolic phenotype different from non-IDH mutated cancer cells." (PMID 27144334, 2016). "Hypoxia induced the expression of lactate dehydrogenase A, as described in other cell lines, but failed to have any influence on gemcitabine induced inhibition of cancer cell proliferation, when evaluating 6606PDA or 7265PDA cells." (PMID 27486761, 2016). "Interestingly, we highlighted evidences that CAV1 interacts with known mediators of altered metabolism, e.g. LDHA, PKM2 and FASN, which are currently being studied as cancer drug targets." (PMID 27852311, 2016). "Elevated phosphorylation of LDHA and PKM2 was detectable in all analysed cancer subtypes." (PMID 25880801, 2015). "Additionally, HIF-1α directly controls the expression of LDHA; HIF-1α and LDH5 are commonly expressed at high levels in cancer cells." (PMID 25635878, 2015). "The qRT-PCR analysis normalized to the LDHA internal house-keeping gene control expression showed a statistically significant reduction in CD44 expression of liposomal CDF treated tumors, confirming the effect of CDF on CD44hi expressing cancer stem cells." (PMID 26098778, 2015). "In this context glycolysis-related proteins may act as detoxifying system (LDHA, TKTL1) of increased ATP producing (and ROS generating) OXPHOS-related proliferating cancer cells." (PMID 25048361, 2014).
cancer (continued). "Expression of mammalian LDHA and LDHB is regulated during development and is tissue specific; therefore, alterations in the LDH levels serve as indicators of pathologic involvement and cancer development." (PMID 25372838, 2014). "LDHA and LDHB proteins are differentially regulated in cancer cells." (PMID 24280423, 2013). "In addition, we present evidence for increased LDHA and SOD2 expression in SDHB-PHEOs/PGLs, proteins that have been proposed as promising therapeutic targets in other cancers." (PMID 22859959, 2012). "Inhibition of LDHA or PDK1 using the chemical inhibitors oxamate and dichloroacetate (DCA) respectively, has been shown to counter the Warburg effect and apoptosis resistance in cancer cells." (PMID 21541279, 2011). "Thus, our experiments revealed that silencing LDHB, but not LDHA, augments RSL3-induced loss of viability in cancer cells." (PMID 40090955, 2025). "In addition, the results showed increased transcription of the LDHA gene together with a trend of higher LDHA protein levels and elevated LDH activity in cancer tissue, suggesting an increased lactate production capability in CRC compared to healthy colon tissue." (PMID 40045444, 2025). "Here, we demonstrate that LDHB, but not LDHA, is essential for mitotic progression in cancers." (PMID 40940446, 2025). "Furthermore, elevated expression and activity of key metabolic genes, including hexokinase 2 (HK2), pyruvate kinase muscle 2 (PKM2) and lactate dehydrogenase A (LDHA), have been documented in various human cancers and are correlated with poorer patient survival outcomes." (PMID 39661026, 2024). "For instance, both BRCA and OV showed log-rank p-values greater than 0.05, indicating that individual LDHA gene expression alone may not be suitable for prognostic prediction in these specific cancers." (PMID 38198170, 2024). "However, our analysis did not reveal a significant association between LDHA CNV and overall survival (OS) in these cancer types (p > 0.05)." (PMID 38198170, 2024). "However, SCC formed despite lack of LDHA, suggesting that cancer cells do not necessarily rely on glucose metabolism for their growth and transformation." (PMID 39303037, 2024). "In this study, we explored the LDHA expression in EC tissues through the TCGA database and HPA database and found that both mRNA and protein levels of LDHA were upregulated in EC tissues compared to normal endometrial tissues, similar to the findings in other cancers." (PMID 39582531, 2024). "Therefore, the development of LDH inhibitors has become a hot topic of discussion among researchers in this field, and several preclinical studies have analyzed the effects of selective and non-selective inhibitors of LDHA on cancer cells." (PMID 36811010, 2023). "Similarly, use of other LDHA inhibitors and comparing the genetic inhibition of LDHA with that or its pharmacological inhibition will reveal the impact of non-enzymatic and non-canonical functions of LDHA in promoting growth of cancer cells." (PMID 35982980, 2022). "Notably, the NAD+ regenerating enzyme LDHA requires tyrosine phosphorylation to control NAD homeostasis, and it has recently been shown that kinase inhibitors cooperate with metformin to target a variety of cancer cells." (PMID 36428689, 2022). "Besides, it has been observed in several studies that inhibition of LDHA causes no significant toxic effect on normal tissue, which makes LDHA a promising therapeutic target in cancer." (PMID 36072431, 2022). "Furthermore, it was found that upregulation of LDHA ensures efficient aerobic glycolysis in cancer cells, but the enzyme is not required for healthy cells under normal conditions." (PMID 36230492, 2022).
cancer (continued). "It followed this mechanism: increase the uptake of glucose by cancer cells by up-regulating the expression of GLUT1, and speed up the metabolism from glucose to pyruvate, and promote the conversion of pyruvate to lactic acid by up-regulating the expression of LDHA." (PMID 35156520, 2022). "Altogether, our data suggest that LDHA and POU1F1 could be important therapeutic targets in cancer." (PMID 33714987, 2021). "In addition to MPC1, the “intersection point” between glycolysis and OXPHOS, we also found the increased expression of lactate dehydrogenase A (LDHA), an enzyme catalyzing the conversion of pyruvate and lactate thus promoting glycolysis and suppressing OXPHOS, in HGLO subgroup across cancer types." (PMID 34030708, 2021). "The potential role of LDHA gene and its isoenzyme, i.e., LDH5 as a prognostic marker in cancer patients, as well as a predictor of response to RT and CTX, or even the main objective in cancer treatment and radiosensitization, is widely discussed (reviewed in:)." (PMID 34208601, 2021). "Unlike that seen for LDHA, metastatic cancers usually show reduced LDHB expression due to promoter hypermethylation or altered glycolytic signaling; low LDHB levels have been associated with poor prognosis in different cancers." (PMID 33804985, 2021). "Through suppressing the key of enzymes of glycolysis LDHA and mitochondrial metabolism PDK1, induced by TGF-β1, the mesenchymal subtype markers N-cadherin and Vimentin are negated, suggesting that the metabolic reprogramming is directly related to cancer metastasis." (PMID 34257808, 2021). "LDHA, an isoform of LDH, is predominantly expressed in cancer cells as a transcriptional regulation product and is activated by post-translational modifications such as phosphorylation and acetylation to increase lactate production during tumor progression and metastasis in cancer." (PMID 33809480, 2021). "Transcriptome analysis showed that the expression of glycolysis-related genes, such as LDHA and ENO2, significantly changed in fibroblasts when they were cocultured with cancer cells with high metastatic potential compared to fibroblasts incubated with cancer cells with low metastatic potential." (PMID 32555715, 2020). "Of note, PIN1 crucially impacts EGFR-promoted Warburg effect in cancer cells by inciting nuclear localization of the Pyruvate Kinase 2 (PKM2), which induces c-MYC expression, resulting in turn in the upregulation of the glucose transport protein 1 (GLUT1) and lactate dehydrogenase A (LDHA)." (PMID 30873382, 2019). "Moreover, in cancer cells, pyruvate produced from glycolysis was converted to lactate by lactate dehydrogenase A (LDHA) rather than acetyl-CoA." (PMID 31367191, 2019). "Thus, targeting LDHA or/and LDHB can create the new opportunity to combat cancer cells." (PMID 31035592, 2019). "The tyrosine kinases involved in the Y10 phosphorylation of LDHA are HER2, the avian sarcoma viral oncogene v-src homolog (Src) and the Fibroblast growth factor receptor 1 (FGFR1), this phosphorylation promotes the Warburg effect and pro-invasive and pro-metastatic potential of cancer cells." (PMID 31737570, 2019). "Furthermore, inhibition of LDHA activity diminished the enhanced glucose consumption and lactate production effects of FOXM1 overexpression, while in vivo studies established that upregulation of FOXM1 promoted LDHA expression, cancer growth and metastasis." (PMID 26269128, 2016). "Cancer cells reprogram their metabolism, and this metabolic reprogramming in cancer cells is regulated by several oncogenic genes, including the PI3K/Akt, Myc, or hypoxia-inducible factor (HIF) that serve to increase glucose uptake, glycolysis, and transcription of LDHA." (PMID 26062441, 2015).
cancer (continued). "Besides, circVAMP3 is the first circRNA found to interact directly with LDHA, which promotes phosphorylation at the Y10 site of LDHA via fibroblast growth factor receptor 1 (FGFR1), enhancing the activity of LDHA, increasing lactate production, and promoting cancer cell proliferation." (PMID 37599427, 2023). "Moreover, our findings suggest that LDHC may exert its effects on genomic integrity and cancer cell survival independent of LDHA/B as we did not observe any compensatory increase in LDHA/B expression for the loss or reduction of LDHC expression." (PMID 34050611, 2022). "Furthermore, two recent studies found that inhibition of LDHA in glioblastoma cell lines with either oxamate or the selective inhibitors, NHI-1 and NHI-2, improved chemotherapy and radiation sensitivity and triggered apoptosis and differentiation of cancer stem cells." (PMID 34367959, 2021). "Similarly, Wang et al6 found that activating the Myc/LDHA axis could regulate aerobic glycolysis in HCC cells and promote tumorigenesis, Zhang et al26 also reported that accelerating c-Myc degradation may enhance aerobic glycolysis in HCC cells, thereby promoting cancer progression." (PMID 40260316, 2025). "In this study, we found that LDHA expression downregulated in KICH samples compared to the normal samples, but it was high-expressed in most cancers." (PMID 37925501, 2023). "On the other hand, none of the dHCPPIs was the same for all cancer types studied, and five interactions were the same in at most seven different cancers (i.e., CAV1-CTNNB1, COL1A1-IGFBP3, LDHA-LDHB, PCNA-GAPDH, and PSMB7-PSMB3)." (PMID 36422095, 2022). "Given the significant attention currently focused on metabolic inhibition strategies to combat cancers, it is particularly important to avoid non-physiological cancer cell culture approaches that alter energy metabolism in ways that may artifactually augment vulnerability to LDHA-inhibiting drugs." (PMID 34439843, 2021). "In the non-irradiated cell experiments, the expression levels of LDHA and LDHB were highest in the HMC3 microglial cells, followed by the FaDu cancer cells, then they relatively lower in the THP-1 monocytes." (PMID 34436459, 2021). "Furthermore, LDHA expression is not altered in LDHC high versus LDHC low expressing cancer cells (unpublished data), suggesting that the difference in peptide-specific T cell responses in LDHC high versus LDHC low expressing cells might not be affected by cross-reactivity with LDHA cognate peptides." (PMID 31932876, 2020). "The experiments with targeting LDHA and LDHB showed that LDHB, but not LDHA, controls lysosomal activity and basal autophagic flux of cancer cells." (PMID 31035592, 2019). "Interestingly, LDHA silencing did not further promote the reduction in cell viability induced by RLS3, but actually led to resistance to RSL3 treatment in four cancer cell lines of different origins compared to transfected control cells." (PMID 40090955, 2025). "However, the specific mechanism through which LDHA and LDHB regulate cancer metabolism has not been fully elucidated, and their impact on PCa glycolysis requires further research." (PMID 38764020, 2024). "However, overexpression of LDHA, CAIX, MCT4, and BSG has only been reported in other types of cancer, but not in CC." (PMID 36678382, 2022). "Indeed, upon TH treatment, cancer cells reinforce the key features of aerobic glycolysis such as lactate production, PKM2 and LDHA expression, and increment ECAR, without affecting the oxygen consumption rate." (PMID 34205977, 2021). "Regarding the impact of macrophages and hypoxia on cancer cells, we found that despite the increased levels of glucose consumption and SLC2A1 expression, there was no increase of lactate production, despite the increase in LDHA expression and acidosis." (PMID 32231135, 2020).